SERPINB6 (serpin family B member 6)
Description:
May be involved in the regulation of serine proteinases present in the brain or extravasated from the blood (By similarity). Inhibitor of cathepsin G, kallikrein-8 and thrombin. May play an important role in the inner ear in the protection against leakage of lysosomal content during stress and loss of this protection results in cell death and sensorineural hearing loss.
Synonyms: CAP; PI-6; PI6; PTI; DFNB91; MSTP057; SPI3
Tractability: Antibody: its Gene Ontology location is reachable by antibodies, with high confidence. PROTAC: ubiquitination databases record sites on it; its protein half-life has been measured.
Gene: Protein-coding gene on chromosome 6 (2,948,158 to 2,972,375, reverse strand). Ensembl gene ENSG00000124570.
Subcellular location: Cytoplasm
Subcellular location (Human Protein Atlas): Centrosome
Pathways (Reactome):
Hemostasis: Dissolution of Fibrin Clot
Immune System: Neutrophil degranulation
Gene Ontology:
Molecular function: protease binding; serine-type endopeptidase inhibitor activity
Biological process: cellular response to osmotic stress; sensory perception of sound
Cellular component: cytoplasm; extracellular exosome; extracellular matrix; extracellular region; nucleus; serine protease inhibitor complex; cytosol; ficolin-1-rich granule membrane; plasma membrane; secretory granule membrane; tertiary granule membrane
Genetic constraint (gnomAD): Loss-of-function variants: 14 observed, 24.41 expected, observed/expected ratio (o/e) 0.57, 90% interval 0.38 to 0.9. The upper end of that interval is the gene's LOEUF score, 0.9, which puts it in group 3 of 6, group 1 being the genes least tolerant of losing a copy. Missense variants: 400 observed, 484.32 expected, observed/expected ratio (o/e) 0.83, 90% interval 0.76 to 0.9. Synonymous variants: 168 observed, 179.76 expected, observed/expected ratio (o/e) 0.93, 90% interval 0.82 to 1.06.
Gene-disease validity (ClinGen):
ClinGen rates the evidence that SERPINB6 causes each of these diseases.
nonsyndromic genetic hearing loss (autosomal recessive): Moderate.
Homologues: Orthologues: chimpanzee SERPINB6 (99% identical), macaque SERPINB6 (97% identical), pig SERPINB6 (81% identical), dog SERPINB6 (78% identical), mouse Serpinb6a (77% identical), guinea pig SERPINB6 (75% identical), rat Serpinb6a (74% identical), mouse Serpinb6b (72% identical), rat Serpinb6b (72% identical), mouse Serpinb6c (68% identical), rat Serpinb6e (59% identical), mouse Serpinb6d (59% identical), and 2 more. Paralogues in human: SERPINB8 (66% identical), SERPINB9 (63% identical), SERPINB1 (52% identical), SERPINB2 (49% identical), SERPINB4 (49% identical), SERPINB10 (48% identical), SERPINB3 (48% identical), SERPINB13 (44% identical), SERPINB11 (44% identical), SERPINB12 (43% identical), SERPINB7 (39% identical), SERPINC1 (38% identical), and 24 more.
Diseases named in the same sentence as SERPINB6 in open-access papers:
SERPINB6 is named in the same sentence as 32 diseases in open-access papers, as found by Europe PMC text mining. Sharing a sentence is not in itself a finding about the gene and the disease. The quoted sentences say what the papers report.
deafness (4 papers, 2018 to 2024). An inherited or acquired condition characterized by the complete loss of the ability to hear from one or both ears. "SERPINB6 gene is associated with deafness, featured as progressive, age-related sensorineural hearing loss." (PMID 35911393, 2022). "The del(GJB6-D13S1830), SERPINB6, TMIE, COCH, ESPN, ACTG1, GJB3, and KCNQ4 mutations were infrequently associated with deafness in the Moravian-Silesian population." (PMID 30344259, 2018). "Additionally, mutations in SERPINB6 and RIPK1 are associated with autosomal recessive (ar) deafness (#613453) and immunodeficiency (#618108), respectively." (PMID 39360045, 2024).
breast carcinoma (1 paper, 2024). "Serpinb6, a protease inhibitor, has also been associated with oestrogen metabolism in the context of breast cancer." (PMID 39518930, 2024).
colon cancer (1 paper, 2025). "In colorectal cancer, SERPINB6 was reported to be linked to the serrated route of colon tumourigenesis and promoted colon cancer cell line proliferation." (PMID 40665565, 2025).
colorectal cancer (1 paper, 2025). A primary or metastatic malignant neoplasm that affects the colon or rectum. "Recent research indicates that elevated SERPINB6 is associated with the development of hepatocellular carcinoma (HCC) and may play a role in advanced proliferation, migration and antioxidant stress resistance of colorectal cancer cells." (PMID 40665565, 2025).
glioblastoma (1 paper, 2025). The most malignant astrocytic tumor (WHO grade IV). "We observed that SERPINB6 mRNA was significantly upregulated in 12 out of 33 cancer types, including glioblastoma (GBM) and brain lower grade glioma (LGG), compared to normal tissues." (PMID 40665565, 2025).
glioma (1 paper, 2025). A benign or malignant brain and spinal cord tumor that arises from glial cells (astrocytes, oligodendrocytes, ependymal cells). "Higher‐grade gliomas, which are associated with poor prognosis, showed increased SERPINB6 expression compared to lower grades." (PMID 40665565, 2025). "In summary, our findings indicate that SERPINB6 is upregulated in glioma and is closely associated with established prognostic and diagnostic markers." (PMID 40665565, 2025). "The diagnostic value of SERPINB6 was affirmed by ROC and time‐dependent ROC curve analyses, demonstrating moderate accuracy (AUC > 0.7) in glioma prediction." (PMID 40665565, 2025). "Further, we examined the relationship between SERPINB6 expression and various clinical characteristics in glioma." (PMID 40665565, 2025). "Our research further demonstrates that the upregulation of SERPINB6 promotes the malignant characteristics of glioma in both in vivo and in vitro models." (PMID 40665565, 2025). "To elucidate the functional impact of SERPINB6 on glioma, we established stable SERPINB6 knockdown in SNB19 and U87 cells using siRNAs (shSERPINB6‐1 and shSERPINB6‐2)." (PMID 40665565, 2025). "This study utilised bioinformatics methods and in vitro and in vivo experiments to assess the expression, function and potential mechanisms of SERPINB6 in the development of glioma." (PMID 40665565, 2025). "Collectively, these findings indicate that SERPINB6 significantly enhances the tumorigenic potential of glioma." (PMID 40665565, 2025). "The results indicated a significant elevation of SERPINB6 in glioma tissues, a finding consistent with increased expression in glioma cell lines (SNB19, U87, A172, U251) compared to normal human astrocytes (NHAs)." (PMID 40665565, 2025). "Our study found that SERPINB6 plays a carcinogenic role in glioma, and its expression level is significantly negatively correlated with patient prognosis." (PMID 40665565, 2025). "To gain insight into the molecular mechanisms by which SERPINB6 mediates the malignant phenotype in glioma, we first identified differentially expressed genes (DEGs) between SERPINB6‐high and SERPINB6‐low expression samples using the limma package." (PMID 40665565, 2025). "Particularly noteworthy is the mechanism of SERPINB6 in promoting EMT in glioma, which is achieved through the activation of the PI3K/AKT/mTOR signalling pathway." (PMID 40665565, 2025). "To evaluate the clinical relevance of SERPINB6 in glioma, we conducted qRT‐PCR and western blot assays on five pairs of clinical glioma and normal tissues." (PMID 40665565, 2025). "This is particularly relevant for IDH wildtype gliomas, where high SERPINB6 expression correlates with aggressive phenotypes and poor response to standard therapies." (PMID 40665565, 2025). "This knowledge gap underscores the need to define the unique functional and molecular contributions of SERPINB6 in glioma pathogenesis." (PMID 40665565, 2025). "We observed that SERPINB6 is highly upregulated in glioma tumours and cells, and its expression is negatively correlated with patient prognosis." (PMID 40665565, 2025). "Collectively, these data strongly suggest that SERPINB6 drives the malignant behaviour of glioma cells primarily through the activation of the EMT process, mediated by the PI3K/AKT/mTOR pathway." (PMID 40665565, 2025). "Conversely, SERPINB6 overexpression produced the opposite effect, indicating that SERPINB6 is a key driver of EMT in glioma." (PMID 40665565, 2025). "The inhibition of this pathway effectively counteracts the malignancy‐promoting effects of SERPINB6, underscoring its potential as a therapeutic target in glioma treatment." (PMID 40665565, 2025). "The study also found that inhibiting SERPINB6 expression can hinder the epithelial‐mesenchymal transition (EMT) of glioma cells." (PMID 40665565, 2025).
glioma (continued). "To explore SERPINB6 expression in glioma, we initially analysed its expression in human cancer and normal tissues, utilising data from the TCGA & CGGA database." (PMID 40665565, 2025). "Specifically, SERPINB6 expression was markedly higher in glioma tissues relative to controls." (PMID 40665565, 2025). "However, existing studies on SERPINB6 have predominantly focused on peripheral cancers, with limited exploration of its role in central nervous system malignancies, particularly glioma." (PMID 40665565, 2025). "Since the enrichment analysis found that SERPINB6 might be involved in the immune response of gliomas, we examined the relationship between SERPINB6 expression and immune cell infiltration levels through ssGSEA analysis." (PMID 40665565, 2025). "In our study, SERPINB6 is highly upregulated in tumour samples and cells of glioma patients." (PMID 40665565, 2025). "In our study, we focused on the biological function of SERPINB6 in glioma." (PMID 40665565, 2025). "Therefore, investigating whether SERPINB6 targets the PI3K/AKT/mTOR axis could be of significant importance in glioma management." (PMID 40665565, 2025). "Most critically, SERPINB6 induces EMT and enhances the malignancy of glioma by activating the PI3K/AKT/mTOR pathway, suggesting its potential as a target in glioma treatment intervention." (PMID 40665565, 2025). "Our findings that SERPINB6 drives glioma progression via PI3K/AKT/mTOR‐mediated EMT align partially with its roles in other cancers, yet also highlight glioma‐specific mechanisms." (PMID 40665565, 2025). "By activating the PI3K/AKT/mTOR pathway, SERPINB6 promotes EMT in glioma, demonstrating its great potential as a new target for glioma treatment." (PMID 40665565, 2025). "Kaplan–Meier survival analysis further revealed that high SERPINB6 expression correlated with lower overall survival (OS), disease‐specific survival (DSS), and progression‐free interval (PFI) in glioma patients." (PMID 40665565, 2025). "Our study proves that SERPINB6 functions by promoting proliferation and EMT in gliomas." (PMID 40665565, 2025). "Functionally, overexpression of SERPINB6 promoted proliferation and EMT of glioma cells." (PMID 40665565, 2025). "Critically, no prior study has investigated whether SERPINB6 modulates EMT in glioma through the PI3K/AKT/mTOR signalling pathway—a key driver of glioma." (PMID 40665565, 2025).
melanoma (1 paper, 2011). A malignant, usually aggressive tumor composed of atypical, neoplastic melanocytes. "In contrast, stage II melanoma patients showed a positive and higher correlation coefficient (r = 0.91) between serpin peptidase inhibitors (SERPINB2 and SERPINB6) in comparison to stage IV melanoma patients (r = -0.61)." (PMID 22032772, 2011).
ovarian carcinoma (1 paper, 2018). A malignant neoplasm originating from the surface ovarian epithelium. "Expression changes and possible functional impact of ACTN1, MPST, ERP29 and SERPINB6 are reported for several cancers, but not for ovarian cancer." (PMID 29344361, 2018).
prion disease (1 paper, 2022). A transmissible disease that is caused by a protein that is able to induce abnormal folding of normal cellular proteins, leading to characteristic spongiform brain changes, which are associated with neuronal loss without an inflammatory response. "Our analysis revealed that, besides the already observed upregulation of SERPINA3 in patients with prion disease and AD, SERPINB1, SERPINB6, SERPING1, SERPINH1, and SERPINI1 were dysregulated in sCJD individuals compared to controls, while only SERPINB1 was upregulated in AD patients." (PMID 35416570, 2022).
steatosis (1 paper, 2025). Increased lipid within the cytoplasm of cells. "The study identified five circulating proteins associated with the steatosis grade in the liver: Cathepsin O (CTSO), Cadherin 2 (CDH2), Leukocyte immunoglobulin-like receptor subfamily A member 5 (LILRA5), and Serpin B6 (SERPINB6); and Prolyl endopeptidase (FAP)." (PMID 39017916, 2025). "The candidates to be combined in future algorithms for steatosis are CTSO, CDH2, LILRA5, SERPINB6, and FAP." (PMID 39017916, 2025).
varicocele (1 paper, 2020). A condition characterized by the dilated tortuous veins of the spermatic cord with a marked left-sided predominance. "Further, WB analysis of the immunoprecipitated proteins ANXA2 and SERPINB6 involved in the same network confirmed the proteins associated with the oxidative stress response are acetylated in the spermatozoa of varicocele patients." (PMID 32365753, 2020).
cancer (7 papers, 2009 to 2025). A tumor composed of atypical neoplastic, often pleomorphic cells that invade other tissues. "Our study shows the key role of PI3K/AKT/mTOR in regulating SERPINB6's maintenance of cancer cell migration and proliferation." (PMID 40665565, 2025). "Two putative oestrogen response elements have been identified in the region upstream of the Serpinb6 transcriptional start site, and Serpinb6 is regulated by 17β-oestradiol in oestrogen receptor-positive cancer cells." (PMID 39518930, 2024). "The role of SERPINB6 has been proven crucial in programmed necrosis and cancer progression." (PMID 40665565, 2025). "Pan-cancer drug prediction analysis on the serpin superfamily was performed based on the CTRP database and the GDSC database, in which SERPINB6, SERPINE1, and SERPINH1 could predict most of the commonly used chemotherapy drugs." (PMID 37091161, 2023).
tumor (7 papers, 2013 to 2025). "In line with our in vitro findings, SERPINB6 knockdown resulted in reduced tumour volume and weight compared to the control group, whereas SERPINB6 overexpression led to increased tumour volume and weight." (PMID 40665565, 2025). "To validate the pro‐tumorigenic effects of SERPINB6 in vivo, we conducted experiments in tumour‐bearing Balb/c nude mice." (PMID 40665565, 2025). "Second, SERPINB6, as serpin activity was one gene ontology class enriched in GSEA, and because SERPINB6 inhibits metastasis and tumor progression." (PMID 34789839, 2022). "Additionally, SERPINB6 has been proposed as a prognostic indicator for cervical cancer, further suggesting its potential role in tumour growth and progression." (PMID 40665565, 2025). "From this cohort, 4 out of 5 of the proteins (IDH1, CTSD, PRDX6, and SERPINB6) also showed a statistically significant increase in abundance (12, 2.3, 2.6, and 3-fold, respectively) in the patient tumour samples when compared to the PDX F1 generation in the species-indistinguishable study." (PMID 30404163, 2018).
neurodegenerative disease (1 paper, 2022). A disorder of the central nervous system characterized by gradual and progressive loss of neural tissue and neurologic function. "In this respect, since ubiquitin proteasome system activity is fundamental in preventing the accumulation of misfolded proteins, it is possible that SERPINB6 dysregulation may also have a function in other neurodegenerative diseases." (PMID 35416570, 2022).
SERPINB6 also shares sentences with these, for which no sentence is quoted: infection (6 papers); hearing loss (3); Alzheimer disease (1); anthrax (1); breast tumor (1); colon (1); distal renal tubular acidosis (1); emphysema (1); hepatocellular carcinoma (1); herpes simplex infection (1); Immunodeficiency (1); Intellectual disability (1); liver steatosis (1); myxoma (1); Salmonella Infections (1); schizophrenia (1); sterility (1); stomach cancer (1).